STAT3 (signal transducer and activator of transcription 3)
Diseases named in the same sentence as STAT3 in open-access papers (continued):
Sharing a sentence is not in itself a finding about the gene and the disease.
melanoma (continued). "Stat3 activity increased melanoma invasiveness and is required for active melanogenesis by regulating tyrosinase gene expression and enzyme activity." (PMID 26830149, 2016). "Activation of STAT3 by IL-6 in melanoma cells promotes the expression of Twist and N-cadherin proteins, which are markers of epithelial-to-mesenchymal transition (EMT)." (PMID 31051015, 2016). "Taken together, we suggest that inhibition of STAT3 activation is critical in apigenin-afforded anti-metastatic activity in melanoma." (PMID 26911838, 2016). "In line with that, MEDICA suppressed the IL-6- and HGF-activated phospho-STAT3(Tyr705) in CRC HT29 or PTC BcPAP cells, and the constitutively-active STAT3 in A375 melanoma cells." (PMID 26959890, 2016). "Conditioned medium from STAT3-targeted B16 melanoma and CT26 colon carcinoma cells also altered the surface phenotype of DCs, inducing higher expression levels of DC activation and maturation markers IL-12, CD40, and MHC class II molecules." (PMID 27148255, 2016). "Signal transducer and activator of transcription 3 (STAT3) is emerging as a therapeutic target in melanoma." (PMID 27323414, 2016). "Icariside II exhibited inhibitory effect on STAT3 signaling pathway in human melanoma A375 and SK-MEL-5 cells, epidermoid carcinoma A431 cells, acute myeloid leukemia U937 cells and multiple myeloma U266 cells." (PMID 27649234, 2016). "Melanomas developed through inflammation-dependent mechanisms have high metastatic potential that is dependent on IL-18, which can activate the STAT3 pathway." (PMID 27941650, 2016). "Overexpression of STAT3 partially reversed IT-induced melanoma growth inhibition, which further suggested that STAT3 signaling was involved in anti-melanoma activities of IT." (PMID 27323414, 2016). "Many signaling pathways are involved in melanoma progression and metastasis, including signal transducer and activator of transcription 3 (Stat3) signaling." (PMID 26830149, 2016). "Hyperactivation of the STAT3 pathway, a downstream target of ROS-activated JAK2 kinase signalling, is intimately linked with melanoma development and the acquisition of tumor invasiveness." (PMID 27756874, 2016). "Flow cytometry analyses revealed that the lal−/− MSC-CM treatment showed lower activation of ERK1/2, STAT3, and P38 in B16 melanoma cells compared with that in lal+/+ MSC-CM-treated B16 cells in syngeneic C57BL/6 mice." (PMID 27531897, 2016). "In this study, we demonstrated that IS significantly sensitized human melanoma cells to TRAIL-induced apoptosis through downregulation of cFLIP in a STAT3-dependent way." (PMID 27418138, 2016). "In this study, nifuroxazide, an oral anti-diarrheal agent identified as an inhibitor of Stat3, was evaluated for its potency against melanoma in vitro and in vivo." (PMID 26830149, 2016). "Survivin, BCL-XL, and MCL-1 have been identified as STAT3- targeted genes, which played important roles in melanoma cell growth and survival." (PMID 27323414, 2016). "It has been well recognized that constitutive phosphorylation/activation of STAT3 contributes to the development and growth of melanoma." (PMID 27323414, 2016). "Five pathways wereenriched for genes in the module d-1 (MAPK1, MITF,RAF1, JAK1, and STAT3):pancreatic cancer (P=5.47E-04), melanoma (P=8.52E-03), melanogenesis (P=1.48E-02),acute myeloid leukemia (P=7.67E-03), and cancer pathways (P=3.69E-03)." (PMID 26840709, 2016). "The signal transducer and activator of the transcription 3 (Stat3) signaling pathway plays an important role in melanoma and has been validated as promising anticancer target for melanoma therapy." (PMID 26830149, 2016). "Constitutive activation of the STAT3 signaling pathway is well recognized to play a critical role in human melanoma development and progression by promoting cancer cell growth, survival, migration and invasion." (PMID 26911838, 2016).
melanoma (continued). "STAT3 activation is involved in regulating cell proliferation, angiogenesis, metastasis and inhibition of apoptosis in melanoma." (PMID 27323414, 2016). "Signal transducer and activator of transcription 3 (STAT3) signaling is constantly activated in human melanoma, and promotes melanoma metastasis." (PMID 26911838, 2016). "In this study, nifuroxazide, an antidiarrheal agent identified as an inhibitor of Stat3, was evaluated for its anti-melanoma activity in vitro and in vivo." (PMID 26830149, 2016). "In conclusion, our study shows that inhibition of the STAT3 signaling pathway contributes to the anti-metastatic effect of apigenin in melanoma." (PMID 26911838, 2016). "Our data not only reveal a novel anti-metastasis mechanism of apigenin but also support the notion that STAT3 is an attractive and promising target for melanoma treatment." (PMID 26911838, 2016). "Taken together, these results strongly indicated that fad104 negatively regulates the phosphorylation level and transcriptional activity of STAT3 in melanoma cells." (PMID 25671570, 2015). "STAT3 phosphorylation promotes oncogenesis in a variety of tissues including melanoma and represents a valid target for novel drugs." (PMID 26329521, 2015). "In fact, the majority of melanoma cell lines and tumor specimens display constitutively activated STAT3." (PMID 25671570, 2015). "Our data suggests that LIFr enhances STAT3 production and activation consequently modifying melanoma cell features." (PMID 26329521, 2015). "In this study, we elucidated for the first time that FAD104 regulated invasion and metastasis of melanoma cells through inhibition of STAT3 activity." (PMID 25671570, 2015). "A previous study showed that ERp57 in the ER lumen negatively regulates STAT3 activation in mouse normal fibroblast cells, whereas the ERp57-STAT3 interaction in the cytosol and nucleus contributes to the activation of STAT3 in melanoma cells." (PMID 25605256, 2015). "Inhibition of STAT3 in melanoma-bearing mice prevents the effects of A2B receptor stimulation on VEGF levels." (PMID 26317647, 2015). "FAD104 interacted with STAT3 and down-regulated the phosphorylation level of STAT3 in melanoma cells." (PMID 25671570, 2015). "With regard to the nuclear function of ERp57, it is noteworthy that the nuclear localization of ERp57 is associated with paclitaxel resistance of ovarian cancer cells and positively regulates STAT3 activity in melanoma cells." (PMID 25605256, 2015). "Instead, eliminating LIFr in melanoma cells markedly reduced STAT3 mRNA expression and inactivated STAT3 by inhibiting its phosphorylation." (PMID 26329521, 2015). "Melanoma-bearing mice were treated with highly selective STAT3 inhibitor S3I-201, which preferentially inhibits STAT3 phosphorylation and STAT3 DNA-binding activity." (PMID 26317647, 2015). "It has been shown to inhibit STAT3 phosphorylation and activity in melanoma cells 20, ovarian and endometrial cancer cells 21, and small-cell lung cancer cells." (PMID 25573684, 2015). "First, STAT3 constitutive activity was shown to directly up-regulate Hif-1α transcription in melanoma cells, and to increase HIF-1α protein levels in several tumor cell types (e.g., breast, kidney, ovary, prostate, melanoma), correlating with EMT and invasion." (PMID 26106584, 2015). "In this report, we show that fad104 suppressed the invasion and metastasis of melanoma cells via the inhibition of STAT3 activity." (PMID 25671570, 2015). "Our results support these findings and show that that TGFβ-induced LIF expression through activation of STAT3 further leads to p21 gene transcription and TGFβ-mediated cell cycle arrest and apoptosis in melanoma." (PMID 25885043, 2015). "In summary, we demonstrated that fad104 suppresses the invasion and metastasis of melanoma cells and is closely involved in negative regulation of the STAT3 signaling pathway." (PMID 25671570, 2015).
melanoma (continued). "Taken together, these results suggest that FAD104 interacts with STAT3 in melanoma cells and the N terminus of FAD104 is required for this interaction." (PMID 25671570, 2015). "It is reported that STAT3 is the central signaling protein that enhances the growth and progression of melanoma cells." (PMID 25671570, 2015). "In a previous study, it was demonstrated that miR-17 targets STAT3 in tumor microenvironment in melanoma mouse model and it was also supported by computational studies which showed STAT3 as a putative target of miR-17." (PMID 26551008, 2015). "Activation of STAT3 serine-727 and tyrosine-705 phosphorylations is promoted by BRAF(V600E) activity, whereas MEK inhibition decreases STAT3 phosphorylation in NRAS-mutant melanoma." (PMID 26116372, 2015). "In summary, our results for the first time establish STAT3 as a critical player that renders anoikis resistance to melanoma cells and enhance their metastatic potential." (PMID 25216522, 2014). "In the current study, we established the role of STAT3 in anoikis resistance and metastasis in melanoma in vitro and in vivo." (PMID 25216522, 2014). "Induction of angiogenesis: STAT3 has been shown to augment tumor angiogenesis in multiple cancer types, such as melanoma, pancreatic cancer, cervical cancer and renal carcinoma." (PMID 24995504, 2014). "Taken together, these results establish the role of STAT3 in anoikis resistance and migration in melanoma cells." (PMID 25216522, 2014). "Inhibition of Jak/Stat3 signalling abrogated the phosphorylation of MLC for melanoma cells thus establishing this pathway as a major driver of contractility also in fibrosarcomas." (PMID 25119572, 2014). "In order to validate the critical role of STAT3 in anoikis resistance in the in vivo model, melanoma tumor xenograft experiments were performed in SCID-NSG mice." (PMID 25216522, 2014). "In the current study, we have established a critical role of STAT3 in anoikis resistance in vitro and in vivo in melanoma." (PMID 25216522, 2014). "We over-expressed STAT3 by transfecting STAT3 expressing plasmid in four melanoma cell lines (SK-MEL-28, SK-MEL-2, SK-MEL5 and MeWo) and performed anoikis assay." (PMID 25216522, 2014). "Curcumin was also reported to be able to reverse inhibition of constitutive STAT3 in multiple melanoma cells and inhibit the translocation of STAT3 in multiple melanoma cells." (PMID 24743778, 2014). "Taken together, these results once again conclusively established the role of STAT3 in anoikis resistance in melanoma." (PMID 25216522, 2014). "These cytotoxic effects of BBMD3 are mediated through inhibition of the Jak2/STAT3 signaling pathway in melanoma cells and activation of the stress-response JNK pathway in osteosarcoma cells, respectively." (PMID 24732116, 2014). "In summary, miR-17 targeted STAT3, promoted Jurkat-cell mitosis and proliferation during co-culture with melanoma B16 cells." (PMID 25594054, 2014). "In conclusion, we report a novel characteristic of STAT3 in promoting resistance to anoikis in melanoma." (PMID 25216522, 2014). "Our results showed that PL treatment significantly decreased the phophorylation of STAT3 at Y705 in a concentration-dependent manner in all the melanoma cell lines." (PMID 25216522, 2014). "Since it is well known that inhibition of STAT3 signalling can induce apoptosis in tumor cells we determined the apoptotic effects of AZD1480 in different murine melanoma cell lines in vitro." (PMID 25149535, 2014). "Accumulating evidence suggests that elevated activity of STAT3 pathway is essential for the ability of melanoma cells to evade the immune system." (PMID 25594054, 2014). "Inhibition of phosphorylated STAT3 has been shown to increase efficacy of tumor necrosis factor- (TNF-) alpha for melanoma." (PMID 25101298, 2014). "As a proof-of-principle, we tested the role of STAT3 in the metastasis of melanoma in the animal model." (PMID 25216522, 2014).
melanoma (continued). "As compared to adherent cells, anoikis resistant melanoma cells exhibited significantly increased expression and phosphorylation of STAT3 at Y705." (PMID 25216522, 2014). "The signal transducer and activator of transcription (STAT3) protein is constitutively activated in approximately 50 to 90% of human cancers, including melanoma." (PMID 25594054, 2014). "In our study, we found that microRNA-17 was able to target STAT3 in tumor microenvironment, thus inhibited melanoma tumor growth by stimulating the tumor infiltrating CD8+ T cells response." (PMID 25594054, 2014). "All these networks were associated to intracellular signaling pathways known to be active in MDSCs (SRC, Grb2, Ras, Stat3, NF-κB and MAPKs), some of them melanoma MDSC-specific targets such as STAT3." (PMID 25151659, 2014). "As expected from the role of STAT3 for lymphocytes, its expression was significantly higher in PBLs than in the melanoma cell lines (p < 0.0001; Kruskal–Wallis)." (PMID 25593920, 2014). "Here, however, we did not observe a significant difference in endogeneous STAT3 mRNA for PBLs or for melanoma cell lines depending on the STAT3 rs4796793 genotype." (PMID 25593920, 2014). "Taken together, these results demonstrated that STAT3 plays a very important role in metastasis of melanoma tumors in vivo." (PMID 25216522, 2014). "As compared to adherent cells, a remarkable phophorylation of STAT3 at Y705 was observed in all the five melanoma cell lines cultured under anchorage-independent conditions and resisted anoikis." (PMID 25216522, 2014). "They showed that MEK inhibitor induced STAT3 activation results in increased melanoma cell invasion." (PMID 24970815, 2014). "Since our results showed that anoikis resistance was associated with enhanced migratory potential, we performed a wound-healing assay in three STAT3 knock-down and respective STAT3 (WT) melanoma cells." (PMID 25216522, 2014). "We found that the secretome of senescent melanoma cells activates the STAT3 pathway and STAT3 inhibition prevents secretome effects, including the acquisition of tumorigenic properties." (PMID 24344100, 2013). "Constitutive activation or knockdown of STAT3 has been shown to up regulate or suppress IL-8 production in human melanoma cells, respectively." (PMID 24274066, 2013). "The results of three separate experiments showed the increase of NFκB transcriptional activity in melanoma cells transfected with plasmids coding for STAT3 specific control shRNA and siRNA against STAT3." (PMID 24170218, 2013). "The basal survival of melanoma cells is unaffected by STAT3 knockdown—likely due to activation of pro-survival NFκB signaling." (PMID 24170218, 2013). "The inhibition of STAT3 by siRNA completely prevented the regulation of all these genes, reinforcing the notion that STAT3 is a critical mediator of melanoma-initiating features and melanoma aggressiveness." (PMID 24344100, 2013). "It was recently reported that STAT3 inhibitors also restored drug sensitivity of melanoma cells which had acquired resistance to BRAF inhibitors." (PMID 23755373, 2013). "Some studies demonstrated reduced survival of murine melanoma B16 cells depleted of Stat3 by siRNA in vitro and in vivo." (PMID 24170218, 2013). "The protein expression of other transcription factors, namely STAT3, a known critical regulator of melanoma development, and HIF-1α and HIF-2α, respectively, were not influenced by diclofenac." (PMID 23874405, 2013). "Immunofluorescent staining further revealed the presence of persistently activated STAT3 in B cells infiltrating human melanoma." (PMID 23734190, 2013). "Results from these experiments showed that addition of Stat3-expressing B cells in the tumor microenvironment accelerated tumor growth in both B16 melanoma and LLC mouse lung tumor models." (PMID 23734190, 2013).
melanoma (continued). "The JAK-STAT pathway, that promotes survival, growth, and angiogenesis, was reported to increase melanoma B-Met mainly via STAT3 activation by phosphorylation, or downregulation of its inhibitor SOCS-1." (PMID 23750336, 2013). "Apart from E804, 6-bromoindirubin-3-oxime, a bromo derivative of indirubin selectively inhibits JAK/STAT3 signaling in human melanoma cells." (PMID 24199193, 2013). "Western blot with phospho-specific antibodies directed against activated ERK, AKT or STAT3 indicated that melanoma cells of different genetic backgrounds exposed to SSMC displayed a strong activation of STAT3." (PMID 24344100, 2013). "STAT3 also maintains NF-κB activation and retention in the nucleus in melanoma cells and prostate cancer cells." (PMID 23402362, 2013). "Our results demonstrate that CCL2 and IL6, which are present in the SSMC, also promote an activation of STAT3 and that STAT3 silencing prevents the acquisition of the mesenchymal, stemness and melanoma-initiating phenotypes." (PMID 24344100, 2013). "Many clinically relevant molecular changes in melanoma (e.g., BRAFV600E mutation, STAT3 Tyr705 phosphorylation) have also been detected in melanocytic nevi, suggesting early events trigger aberrant growth or transformation." (PMID 24098663, 2013). "This coincides with a report in LU1205 melanoma cells, in which STAT3 transcriptional activities can be activated upon inhibition of ERK and constitutively active ERK signaling resulted in downregulation of STAT3 and STAT5 transcriptional activities." (PMID 24288470, 2013). "To study the crosstalk between STAT3 and NFκB signaling and its role in regulation of cancer cell survival, we used RNA interference (RNAi) to down-regulate STAT3 expression in human melanoma cells." (PMID 24170218, 2013). "In various cancer types, including leukemias and solid cancers of the breast, head and neck, melanoma, prostate, pancreas, and colon, aberrant activation of STAT3 crucially contributes to cancer progression." (PMID 24324713, 2013). "Further mechanistic study revealed that PTX inhibits STAT3 phosphorylation and DNA binding in melanoma cells and that this inhibition was partly mediated through the inhibition of upstream kinases pJAK1 and pJak2." (PMID 24199193, 2013). "As shown by western blot in the three melanoma cell types, STAT3 siRNA efficiently reduced STAT3 expression and the SSMC activated STAT3 compared to the control conditioned medium." (PMID 24344100, 2013). "More importantly, activation of STAT is the key factor for development of melanoma; silencing of STAT3 using short hairpin RNA (shRNA) inhibits the growth of melanoma in tumor-bearing mice." (PMID 23693134, 2013). "We demonstrate an induction of the NFκB activity (verified with three different assays: NFκB-driven luciferase assay, NFκB DNA binding ELISA and detection of phosphorylated IκB) in melanoma cells depleted of STAT3." (PMID 24170218, 2013). "Our findings also point out, both in vitro and in vivo, the key role of the STAT3 signaling cascade in acquisition of the stemness and mesenchymal phenotype as well as the melanoma-initiating properties mediated by SSMC." (PMID 24344100, 2013). "Collectively these observations indicate that STAT3 is a key player in the transition between melanoma initiating cells and their more differentiated progeny." (PMID 24344100, 2013). "The inhibition of STAT3 induces apoptosis in melanoma cells and suppresses the growth of head and neck tumors in nude mice." (PMID 23950841, 2013). "STAT3 can down-regulate Bcl-xL expression and induce apoptosis in human melanoma A2058 and Jw cell lines." (PMID 23693134, 2013). "The results of three separate experiments showed the increase of NFκB transcriptional activity in melanoma cells transfected with plasmids coding for STAT3 specific and control shRNA." (PMID 24170218, 2013).